PIEZO1 (piezo type mechanosensitive ion channel component 1 (Er blood group))
Diseases named in the same sentence as PIEZO1 in open-access papers (continued):
Sharing a sentence is not in itself a finding about the gene and the disease.
esophageal squamous cell carcinoma (7 papers, 2022 to 2025). Esophageal squamous cell carcinoma (ESCC) is a type of esophageal carcinoma (EC) that can affect any part of the esophagus, but is usually located in the upper or middle third. "In the case of esophageal squamous cell carcinoma, the downregulation of Piezo1 reduces the migration and invasion of cancer cells." (PMID 36837670, 2023). "Piezo1 channels are expressed in squamous cells of the esophageal mucosa, and recent studies demonstrated that Piezo1 levels are elevated in human esophageal squamous cell carcinoma (ESCC) tumors." (PMID 37781915, 2023).
fibrosis (7 papers, 2022 to 2026). the formation of excess fibrous connective tissue in an organ or tissue in a reparative or reactive process. "Piezo1 channels can detect the bloodstream and shear force and are linked to liver metabolic functions and the progression of fibrosis." (PMID 41017814, 2025). "Future work should clarify the changes in Piezo1 expression in diseases and test perturbations in relevant models (e.g., primary KC isolation and Piezo1 modulation in fibrosis models) to determine its functional significance." (PMID 41017814, 2025). "Therefore, during UUO, tubular epithelial cells, at least partially, through Piezo1, sense stretch or swelling forces in apical plasma membrane and stiff microenvironments in basolateral sides after fibrosis development." (PMID 35230979, 2022).
intervertebral disc degeneration (7 papers, 2022 to 2025). "Current evidence suggests that Piezo1 channels are implicated in the pathogenesis of intervertebral disc degeneration, while transient receptor potential vanilloid type 4 (TRPV4) also contributes to this process." (PMID 38068915, 2023). "Ca2+ serves as a mediator of the inflammatory response triggered by Piezo1 activation through mechanical stretching, ultimately leading to intervertebral disc degeneration." (PMID 38068915, 2023). "Moreover, conditional knockout of Piezo1 (Col2a1-CreERT Piezo1flox/flox) attenuated the mechanical injury-induced intervertebral disc degeneration (IVDD)." (PMID 38553442, 2024).
multiple sclerosis (7 papers, 2022 to 2025). A progressive autoimmune disorder affecting the central nervous system resulting in demyelination. "PIEZO1 appears to have a direct role not only in myelin formation and degradation but also in modulating immune responses associated with multiple sclerosis (MS)." (PMID 40703567, 2025). "Multiple sclerosis, for example, is accompanied by loss of parenchyma stiffness, and the downregulation of Piezo1 in oligodendrocytes has been observed, which might be responsible for demyelination in multiple sclerosis." (PMID 38923822, 2024). "In addition, PIEZO1 has been associated with altered microglial response in neurodegenerative conditions such as Alzheimer’s disease and multiple sclerosis, where it may modulate chronic inflammation, phagocytic clearance of debris, and neuronal survival." (PMID 40863236, 2025). "Remarkably, the data showed significantly lower expression of Piezo1 in the white matter in multiple sclerosis brains compared to its expression in the white matter in healthy controls." (PMID 35722613, 2022). "This theory could be analogous to impaired crosstalk between axonal Piezo2 and Piezo1 of oligodendrocytes in the central nervous system in multiple sclerosis (MS)." (PMID 37108693, 2023). "Taken together, we here show that Piezo1-induced signaling can be used to modulate oligodendrocyte function and that it may be an important player in the pathophysiology of multiple sclerosis." (PMID 35722613, 2022). "This suggests that PIEZO1 may be a future therapeutic target for multiple sclerosis treatment." (PMID 40703567, 2025). "In the future, pharmacological PIEZO1 blockade or biomechanical modulation may preserve BBB integrity, attenuate leukocyte infiltration, and limit neurovascular inflammation in disorders such as multiple sclerosis, vascular dementia, and CNS malignancies." (PMID 40863236, 2025).
oral squamous cell carcinoma (7 papers, 2021 to 2025). "In oral squamous cell carcinoma cells, PIEZO1 is reportedly involved in regulating the proliferation and growth of oral squamous cell carcinoma cells as a transcriptional target of YAP signaling." (PMID 38494915, 2024). "In oral squamous cell carcinoma, elevated Piezo1 induced by YAP signaling was required for cell proliferation." (PMID 35461277, 2022). "Studies by Japanese scholars have shown that Yap can regulate the expression of Piezo1 in oral squamous cell carcinoma cells and further regulate the proliferation and metastasis of squamous cell carcinoma." (PMID 35464728, 2022). "However, it has been reported that Piezo1 could act upstream of YAP in oral squamous cell carcinoma, We speculate that the hierarchical relationship between PIEZO1 and YAP may be dependent on this cell context, or that there is a positive feedback regulation between PIEZO1 and YAP." (PMID 34805150, 2021).
pulmonary edema (7 papers, 2019 to 2025). Accumulation of fluid in the lung tissues causing disturbance of the gas exchange that may lead to respiratory failure. "In pulmonary edema, Piezo1 in endothelial cell mediates pressure-induced lung vascular hyperpermeability via disruption of adhere junctions." (PMID 41034523, 2025). "Elevated microvessel hydrostatic pressure in the lung results in the opening of Piezo1, which mediates disruption of endothelial barrier, leading to pulmonary edema." (PMID 35252406, 2022). "It was recently reported that Piezo1 senses high vascular pressures at the lung endothelial surface and is responsible for vascular hyperpermeability and pulmonary edema." (PMID 33298523, 2021). "Endothelium-specifical deletion of Piezo1 (Piezo1iEC−/−) in mice results in pulmonary endothelial hyperpermeability and pulmonary edema, which may contribute to the reduced lung static compliance in Piezo1iEC−/− mice similar to the decreased lung compliance observed in ALI/ARDS patients." (PMID 36539808, 2022).
type 2 diabetes (7 papers, 2022 to 2025). "This study aimed to elucidate the altered signaling elicited by Piezo1 activation in the arteries of type 2 diabetes." (PMID 38955832, 2024). "We propose that mechanosensing and PIEZO1 play a previously unrecognized role in β-cell function and systemic glucose metabolism and that this mechanism becomes defective in patients with type-2 diabetes." (PMID 35869052, 2022).
acute respiratory distress syndrome (6 papers, 2019 to 2026). Progressive and life-threatening pulmonary distress in the absence of an underlying pulmonary condition, usually following major trauma or surgery. "The mechanical stretching of the alveolar induced by acute respiratory distress syndrome (ARDS) activates the Piezo1 channel, resulting in calcium injection causing type II lung cell apoptosis." (PMID 35751027, 2022). "As intracellular Ca2+-dependent cysteine protease, calpain is also involved in PIEZO1-induced pulmonary endothelial barrier disruption in acute respiratory distress syndrome." (PMID 34568428, 2021). "The mechanisms of lung injury in acute respiratory distress syndrome (ARDS) are not well understood.Piezo1 was recently identified as a mechanotransduction protein." (PMID 31186017, 2019). "Likewise, in a murine model of acute respiratory distress syndrome (ARDS) induced by LPS, resistive breathing exacerbated hypoxemia and inflammation, downregulating Piezo1, a mechanosensitive channel implicated in ventilator-induced injury, underscoring the combined burden on lung and diaphragm." (PMID 41359372, 2026).
asthma (6 papers, 2021 to 2025). "By modulating the mechanical and immune environment of the lungs, PIEZO1 helps to fine-tune the inflammatory response, potentially offering new avenues for asthma treatment by targeting mechano-transduction pathways." (PMID 39664985, 2024). "This review synthesizes recent mechanistic insights into how dysregulated calcium signaling-via transient receptor potential (TRP) channels (e.g., TRPV1, TRPA1), store-operated calcium entry (SOCE), L-type calcium channels (LTCCs), and mechanosensitive Piezo1-drives key asthma phenotypes." (PMID 41437399, 2025). "Interventions targeting calcium-regulated nodes (such as STIM1-Orai1 and Piezo1) may provide a new direction for asthma treatment beyond traditional anti-inflammatory strategies." (PMID 41437399, 2025). "This suggests that PIEZO1 may have therapeutic potential in modulating airway constriction, a key feature of asthma." (PMID 39664985, 2024). "Current research into ion channels in asthma has opened new frontiers in understanding how Ca2+, K+, Cl−, H+, TRP, and Piezo1 channels contribute to immune responses in the disease." (PMID 39664985, 2024).
breast tumors (6 papers, 2019 to 2025). "Both the in vivo and in vitro experiments validated the photothermal conversion efficiency of TiCN and witnessed the efficacy of Piezo1 specific agonist in enhancing the sensitivity of breast tumor to hyperthermia therapy under the 1,064 nm laser irradiation." (PMID 38463518, 2024). "The photothermal nanomaterial called TiCN was used to assess the role of Piezo1 activation in PTT of breast tumor." (PMID 38463518, 2024). "The Piezo1-specific agonist Yoda1 enhanced the effect of TiCN on breast tumor ablation under a 1,064 nm laser." (PMID 38463518, 2024). "This revealed that both EPI (e.g. LLGL2, CLDN4, KRT7, ST14) and MES (e.g. SNAI1, VIM, AP1M1) genes positively correlated with PIEZO1 expression across all quintiles, whilst markers of luminal breast tumors (ESR1, FOXA1, PGR) negatively correlated in all instances." (PMID 38632473, 2024). "Upon the analysis of patients with breast tumors classified by HR status and HER2 status, we found that the HR-negative patients had significantly higher levels of PIEZO1 expression than the HR-positive patients (p < 0.0001)." (PMID 38398074, 2024).
colorectal cancer (6 papers, 2014 to 2025). A primary or metastatic malignant neoplasm that affects the colon or rectum. "In breast and colorectal cancers, Piezo1 upregulation is associated with decreased E-cadherin and increased N-cadherin and Snail expression, indicating its regulatory role in EMT and adhesion remodeling." (PMID 40821847, 2025). "In colorectal cancer, Piezo1 upregulation correlates with poor prognosis." (PMID 40821847, 2025). "Furthermore, the upregulation of Piezo1 expression has been shown to facilitate the invasion and proliferation of colorectal cancer cells." (PMID 36060694, 2022). "Moreover, an in vitro study revealed that Piezo1 gene knockdown can reduce the invasion of colorectal cancer cells, highlighting the regulatory function of Piezo1 in colorectal cancer." (PMID 36060694, 2022).
iron overload (6 papers, 2017 to 2025). "Recent studies demonstrate that constitutive or macrophage-specific expression of a GOF Piezo1 allele in mice disrupts the expression of the iron regulator hepcidin, leading to iron overload." (PMID 41017814, 2025). "It is important to emphasize that the cardiac impairment in GOF PIEZO1 carriers with iron overload and acute decompensated heart failure is reversible, changing traditional understanding of prognoses for iron overload cardiomyopathy." (PMID 41237237, 2025). "In macrophages, PIEZO1 GOF dysregulates hepcidin expression, contributing to systemic iron overload." (PMID 41237237, 2025).
ischemia (6 papers, 2023 to 2026). A hypoperfusion of the BLOOD through an organ or tissue caused by a PATHOLOGIC CONSTRICTION or obstruction of its BLOOD VESSELS, or an absence of BLOOD CIRCULATION. "Previous research suggests that the mechanosensitive ion channel Piezo1 becomes active in response to mechanical stress conditions, including ischemia and trauma." (PMID 41507309, 2026). "In mice, increased IL-6 mRNA and other inflammatory mediators in cardiac ischemia and reperfusion were reduced by cardiac myocyte–specific PIEZO1 deletion, suggesting a role for cardiac myocyte PIEZO1 in regulating IL-6." (PMID 40721314, 2025). "In contrast, in a mouse hindlimb ischemia model, normal mice had significantly better recovery of blood flow after ischemia than Piezo1 knockout mice." (PMID 37876552, 2023). "Ca2+-activated calpains are important in ischemia and downstream from PIEZO1-mediated Ca2+ entry." (PMID 40721314, 2025).
ischemic stroke (6 papers, 2022 to 2026). A stroke disorder caused by obstruction of blood flow to the brain, due to thrombotic (local blood clot formation) or embolic (due to a blood clot or other material traveling from another site) event. "Piezo1 is also associated with ischemic stroke and affects the pathological processes via various mechanisms." (PMID 38923822, 2024). "Beyond astrocytic reactivity, Piezo1 has also been shown to disrupt blood–brain barrier integrity via CaMKII/Nrf2 signaling during ischemic stroke." (PMID 41009567, 2025). "Taken together, these studies demonstrated that high Piezo1 expression is unfavorable for the pathology of ischemic stroke." (PMID 39539343, 2024). "Our data revealed enhanced spiking activity after activation of mechanosensitive Piezo1 channels in trigeminal afferents of the IL hemi-skulls of the ischemic stroke group, as well as prolonged activation of nociceptive TRPV1 channels." (PMID 36293444, 2022). "In addition, we demonstrate that platelet activation induces the mechanosensors Piezo1 and syndecan-1, sensitizing brain endothelial cells to shear-stress alterations characteristic of ischemic stroke." (PMID 42121873, 2026). "Reducing the expression of Piezo1 prevented artery clots in rats and reduces the size of infarcts, which may represent a treatment approach for ischemic stroke." (PMID 39539343, 2024). "Therefore, the modulation of Piezo1 expression in ischemic stroke may be a therapeutic strategy." (PMID 39539343, 2024). "We found that a Piezo1-Ca2+-mediated increase in the proportion of Wnt7b+ astrocytes can regulate glial scar stiffness, which directs the NSC lineage choice during regeneration after ischemic stroke." (PMID 41346705, 2026). "Our data suggest the involvement of mechanosensitive Piezo1 channels capable of maintaining high-frequency spiking activity and of nociceptive TRPV1 channels in trigeminal headache pain responses after experimental ischemic stroke in mice." (PMID 36293444, 2022).
Myocardial fibrosis (6 papers, 2023 to 2026). "In summary, the protective effect of ZBED6 against myocardial fibrosis injury is achieved through the inhibition of Piezo1 transcription, leading to reduced YAP nuclear translocation." (PMID 41555028, 2026). "Overactivation of Piezo1 can promote the release of inflammatory factors, induce cardiomyocyte apoptosis, and enhance fibroblast activity, thereby worsening myocardial fibrosis and decreasing compliance." (PMID 41195420, 2025). "The myocardial fibrosis marker gene Col1a1, Col3a1, and Tgfb1 were downregulated, correlated with the reversal of Piezo1." (PMID 40344385, 2025). "Collectively, these data reveal that collagen histaminylation limits TGM2-dependent crosslinking, softens the extracellular matrix, and inhibits the PIEZO1/ITGB1 axis, thereby mitigating myocardial fibrosis after AMI." (PMID 42270610, 2026). "However, when we activated the expression of Piezo1 at the same time of patch treatment, MI‐induced the dysregulation of calcium influx, myocardial fibrosis, and inflammatory response was not improved to normal level." (PMID 40344385, 2025).